NLRP3 (NLR family pyrin domain containing 3)
Diseases named in the same sentence as NLRP3 in open-access papers (continued):
Sharing a sentence is not in itself a finding about the gene and the disease.
Parkinson disease (continued). "Compounds such as flufenac and mefenac have been shown to inhibit NLRP3 activation, thereby alleviating the symptoms of Parkinson’s disease." (PMID 39058145, 2024). "RNA-seq analysis revealed distinct effects of BFT and the NLRP3 inhibitor MCC950 on Parkinson-related pathways and genes." (PMID 39042624, 2024). "Activation of NLRP3 in microglia exacerbates neuroinflammation and neurodegeneration in Parkinson’s disease regulated by MPTP." (PMID 39030593, 2024). "NEAT1 promotes inflammasome activation in microglia by enhancing NLRP3 transcription, exacerbating neuroinflammation in conditions like Parkinson’s disease." (PMID 39852123, 2024). "In order to further observe the pathological mechanism of Parkinson’s mouse, NLRP3 related apoptosis were explored firstly." (PMID 38683404, 2024). "Studies have shown that NLRP3 inflammasome/pyroptosis is related to various diseases, including diabetic retinopathy and Parkinson’s disease." (PMID 37511451, 2023). "Microglial hyperactivation of the NOD‐, LRR‐, and pyrin domain‐containing 3 (NLRP3) inflammasome contributes to the pathogenesis of Parkinson's disease (PD)." (PMID 37029500, 2023). "While the correlation between pathologies like Alzheimer’s, Parkinson’s, or multiple sclerosis and the role of NLRP3 has been extensively studied, unfortunately, epilepsy, a complex neurological disease, has not received the same level of attention." (PMID 37893198, 2023). "The ability of BHB to suppress pyroptosis via inhibiting the STAT3/NLRP3/GSDMD axis was previously documented in Parkinson’s disease models." (PMID 37841914, 2023). "P38–TFEB signaling was discovered in the investigation of NLRP3 signaling in Parkinson's disease (PD)." (PMID 37655052, 2023). "Other studies have demonstrated a direct relationship between miR-7 and NLRP3 in Parkinson’s disease pathogenesis, to which miR-7 triggers the microglial NLRP3 inflammasome activation." (PMID 37998332, 2023). "Several studies have shown a relationship between NLRP3 inflammatory bodies and neurodegenerative diseases, including Parkinson’s disease (PD) and AD." (PMID 37110714, 2023). "For this reason, NLRP3 inflammasome inhibitors are used to treat a range of diseases from cancer to neurodegenerative conditions like Parkinson’s and Alzheimer’s." (PMID 37313460, 2023). "Neat1 activated the NLRP3 inflammasome and upregulated proinflammatory cytokines by sponging several microRNAs in Parkinson’s disease." (PMID 37614230, 2023). "Neuroinflammation driven by NLRP3 inflammasome in NDs has been proved, such as AD, Parkinson's disease (PD), stroke, and amyotrophic lateral sclerosis (ALS)." (PMID 37125240, 2023). "Owing to the dual effect of Parkinson’s disease and surgical trauma, Aβ accumulation can activate NLRP3 and upregulate the expression levels of IL-1β, IL-18, and Caspase-1 to cause inflammation." (PMID 37232753, 2023). "Although NLRP3 is primarily induced by microglia, recent reports have also demonstrated the role of neuronal NLRP3 in Parkinson’s Disease." (PMID 36812097, 2022). "Safflower flavonoid extract (SAFE) reduced the level of plasma inflammatory factors, inhibiting NLRP3 inflammasome activation in mice, exhibiting significant anti-Parkinson’s disease effects." (PMID 36009120, 2022). "Effectors of pyroptosis are activated and transferred to the membrane to induce glial rupture, releasing more inflammatory mediators, which promote the progression of Parkinson’s disease with NLRP3." (PMID 34775541, 2022). "A clinical study collected serum samples from 12 untreated patients with Parkinson’s disease (aged 63–78 years) and detected a significantly upregulated expression of NLRP3 inflammasome, caspase-1, and IL-1β levels." (PMID 36009120, 2022). "In particular, the overexpression of SNHG1 has been reported to compete endogenous RNA for miR-7 to regulate NLRP3 expression, leading to the activation of the NLRP3 inflammasome and promoting neuroinflammation in Parkinson’s disease." (PMID 35547731, 2022).
Parkinson disease (continued). "The inhibition of the hepatic Nlrp3 protects dopaminergic neurons by attenuating systemic inflammation in a MPTP/p mouse model of Parkinson’s disease." (PMID 36009120, 2022). "The results showed that MPTP-induced NLRP3 inflammasome activation in microglia played a central role in dopaminergic neurodegeneration and Parkinson’s disease." (PMID 34775541, 2022). "A critical role for microglial NLRP3 inflammasome activation in the progression of both dopaminergic neurodegeneration and α-syn pathology has been demonstrated in parkinsonism mouse models." (PMID 35172843, 2022). "Inhibition of HDAC6 attenuates the NLRP3 inflammatory response and protects dopaminergic neurons in experimental models of Parkinson’s disease." (PMID 35910382, 2022). "In the mouse model of fibrillar α-synuclein of Parkinson’s disease, the NLRP3 inflammasome of microglia is activated, resulting in the extracellular release of IL-1β." (PMID 36231090, 2022). "This has been demonstrated in vitro in mouse macrophages and microglia as well as in vivo in the MPTP mouse model of parkinsonism, where DA exerts its inhibitory effect by regulating NLRP3 protein levels through DA receptor signaling." (PMID 35172843, 2022). "In a Parkinson’s disease model, dl-3-butylphthalide salvaged dopaminergic neurons by inhibiting NLRP3 inflammasome and alleviating mitochondrial damages." (PMID 36160384, 2022). "NLRP3 promoted the secretion of IL-1β/18 and pyroptosis to rupture microglia to further release inflammatory factors in Parkinson’s disease." (PMID 34775541, 2022). "NLRP3 inflammasome-mediated neuroinflammation exerts a significant effect on the pathogenesis of Parkinson’s disease." (PMID 36009120, 2022). "For instance, a study showed that SNHG1 was remarkably elevated in LPS-induced BV2 cells, and its depletion mitigated neuroinflammation through the miR-7/NLRP3 axis in Parkinson’s disease." (PMID 35547731, 2022). "Rs7525979 can regulate NLRP3 translation and lead to the accumulation of an ubiquitinated, insoluble form of NLRP3 in Parkinson's disease." (PMID 36051474, 2022). "Another study found that miR-7 targets NLRP3 expression, while miR-7 mimics suppress NLRP3 inflammasome activation and protects dopaminergic neurons against degeneration in a murine model of Parkinson’s disease." (PMID 34750358, 2021). "Inhibition of p38 had a protective effect on Parkinson's disease model via suppressing the activation of NLRP3 inflammasome pathway." (PMID 34930303, 2021). "p38-TFEB pathways promote microglia activation through inhibiting CMA-mediated NLRP3 degradation in Parkinson's disease." (PMID 34930303, 2021). "In mouse models of Parkinson’s disease, the downregulation of miR-30e, miR-190, and miR-7 enables NLRP3 and ASC expression, the cleavage of caspase-1, the release of IL-1β and IL-18 cytokines, and the cell death by pyroptosis." (PMID 34829842, 2021). "Autophagy has also been proven to engulf NLRP3 to play an anti-inflammatory role in Parkinson’s disease." (PMID 32003754, 2020). "The development of Alzheimer’s Disease (AD), Parkinson’s Disease (PD) and Multiple Sclerosis (MS), through varying mechanisms, have been evidenced to prime and activate the NLRP3 inflammasome, which subsequently mediates further inflammation and damage." (PMID 32883606, 2020). "Especially, specific inhibition of NLRP3 by MCC950 by daily oral administration of this molecule allowed disease regression in all mice models of Parkinson’s disease tested." (PMID 31892810, 2019). "Altogether, these findings make the NLRP3 inhibitor MCC950 a good therapeutic for Parkinson’s disease." (PMID 31892810, 2019). "Previous studies showed that the MPTP mouse model of Parkinson's disease, traumatic brain injury, cerebral ischemia-reperfusion injury, and isoflurane-inducedhippocampal inflammation can induce the NLRP3 inflammasome activation." (PMID 30918581, 2019).
Parkinson disease (continued). "Studies have confirmed that genes modulated during the pathogenesis of Parkinson’s disease appear in our regulatory network, and include CD79A and NLRP3 in addition to miRNAs associated with PD models, including miR-142-3p, miR-15b-5p, and miR-590-3p." (PMID 30665415, 2019). "The anti-inflammatory effect was induced by the inhibition of the NLRP3 inflammasome activation through downregulation of ROS in microglia in mice Parkinson’s disease models." (PMID 30233319, 2018). "Interestingly, the druggability of NLRP3 has been recently demonstrated in (neuro) inflammatory disorders such as Parkinson’s disease, amyotrophic lateral sclerosis (ALS) or cardiovascular disease." (PMID 41162989, 2025). "Collectively, these results provide strong evidence that PAL ameliorates motor deficits and dopaminergic neuron death in Parkinson’s disease, and the mechanism may be related to its inhibition of NLRP3 inflammasome activation via promoting mitophagy." (PMID 39096445, 2025). "VTX3232, a CNS-penetrant NLRP3 Inhibitor, is conducting a Phase 2a clinical study to evaluate the safety, tolerability, pharmacokinetics, and pharmacodynamics in participants with Early-Stage Parkinson’s Disease." (PMID 40038816, 2025). "Therefore, the evidence suggests that regulating microglial NLRP3 activation by PARKIN via polyubiquitination ameliorates neurodegeneration in Parkinson’s disease." (PMID 39861194, 2025). "In Parkinson’s, elevated IL-1β and CNS protein inclusions in the gut indicate NLRP3 overactivation." (PMID 41181331, 2025). "FYN can activate NLRP3 inflammatory vesicles and amplify inflammation in Parkinson’s disease." (PMID 40958910, 2025). "Likewise, VTX3232—an orally active, CNS-penetrant, and selective NLRP3 inhibitor—is currently undergoing Phase II evaluation in early-stage Parkinson’s disease." (PMID 40977745, 2025). "Given that microglial activation and NLRP3 inflammasome-mediated neuroinflammation are critical pathological mechanisms in Parkinson’s disease (PD), we employed an in vivo model involving stereotactic injection of LPS into the substantia nigra to induce PD-like pathology." (PMID 40990010, 2025). "A newly discovered function of LncZFAS1 has emerged, demonstrating its role in negatively regulating NLRP3 inflammasome activation and pyroptosis in human neuroblast cells treated with 1-methyl-4-phenylpyridinium, serving as an in vitro model of Parkinson’s disease." (PMID 40307577, 2025). "Also, in a mouse model of Parkinsonism, the dopaminergic neurodegeneration and α-syn pathology is related to microglial NLRP3 inflammasome activation." (PMID 38421496, 2024). "Surprisingly, it observed a suppression of NLRP3 inflammation in the striatum of Parkinson’s mouse." (PMID 38683404, 2024). "Safranal protected the Parkinson’s disease mouse via inhibition of NLRP3 inflammasome activation." (PMID 38683404, 2024). "VTX3232 is another novel oral selective inhibitor of NLRP3 developed by Ventyx Biosciences that can cross the blood‒brain barrier for the treatment of neurodegenerative diseases, including Parkinson’s disease, multiple sclerosis, Alzheimer’s disease and amyotrophic lateral sclerosis." (PMID 38945951, 2024). "However, the evidence supporting NLRP3's involvement in Parkinson's disease from human genetics data is limited." (PMID 37886468, 2024). "And Safranal played a neuroprotective effect on the Parkinson’s disease mouse and its mechanism may be related to the inhibition of NLRP3 inflammasome activation." (PMID 38683404, 2024). "Clinical trials targeting the NLRP3-inflammasome in Parkinson's disease are ongoing." (PMID 37886468, 2024). "Also, miR-7 and miRNA-190 regulate neuroinflammation in Parkinson's disease by binding to NLRP3 inflammasome in a mouse model." (PMID 38421496, 2024). "Furthermore, the IC effect was demonstrated with other NLRP3 inflammasome activators – α-synuclein aggregates – being important players in neuroinflammation in Parkinson’s disease." (PMID 38664730, 2024).
Parkinson disease (continued). "Furthermore, post-mortem tissues from Parkinson’s disease patients demonstrated upregulated Nlrp3 expression in dopaminergic neurons." (PMID 38920626, 2024). "In animal and cellular models of Parkinson’s disease, microglial mitochondrial damage amplifies the Nucleotide-binding oligomerization domain, Leucine-rich Repeat, and Pyrin domain-containing Protein 3 (NLRP3) inflammasome proinflammatory signals." (PMID 39830208, 2024). "The keywords were classified into 10 categories: gut microbiota, Hypothalamic-pituitary-adrenal (HPA) axis, bipolar disorder, probiotics, irritable bowel syndrome, Parkinson’s disease, NLRP3 inflammasome, metabolic syndrome, vagus nerve, and short-chain fatty acids." (PMID 39588103, 2024). "In this review, we address the intricate relationship between mitochondrial dysfunction, oxidative stress, NLRP3 overactivation, and neuroinflammation in the pathogenesis and progression of Alzheimer’s disease (AD), Parkinson’s disease (PD), and amyotrophic lateral sclerosis (ALS)." (PMID 38397838, 2024). "Currently, significant efforts are placed on investigations of the role of NLRP3 in disease progression, especially in sterile conditions like Alzheimer’s, Parkinson’s, cardio-metabolic syndromes and cancer where chronic inflammation has proven to mediate disease progression." (PMID 39188718, 2024). "Mendelian randomization suggests that altering the expression of the NLRP3-inflammasome, IL-1β or IL-18, does not affect Parkinson's disease risk or progression." (PMID 37886468, 2024). "In animal models of Parkinson’s disease, depression, inflammatory pain, and mechanisms, such as ubiquitination, autophagy, and mitophagy, inhibit NLRP3-mediated inflammasome activation, thereby reducing neuroinflammation and oxidative reactions and preserving neuronal activity." (PMID 39030593, 2024). "MLT also attenuated neuroinflammation in the 1-methyl-4-phenyl-1,2,3,6-tetrahydropyridine (MPTP)-induced model of Parkinson’s disease through the suppression of microglial activation, downregulation of the NLRP3 inflammasome components, and inhibition of IL-1β secretion." (PMID 36747075, 2023). "Importantly, α-syn can trigger NLRP3 activation in Parkinson’s disease, leading to α-syn accumulation." (PMID 35431795, 2022). "NLRP3 activation promotes the secretion of the inflammatory cytokine interleukin-1β/18 (IL-1β/18) and induces pyroptosis to rupture microglia to further release inflammatory factor in Parkinson’s disease." (PMID 34775541, 2022). "In the Naringin treated group (NAR+VAN) there is a decreased number of NLRP3 positive cell in the SNc and CPu when compared to the Parkinson's induced group (VAN), this just shows that Naringin inhibits the activation of NLRP3 and production of Tumour Necrosis Factor alpha." (PMID 36660080, 2022). "NLRP3 inflammasome blockade significantly prevents α-syn-induced microglial activation and IL-1β production, preventing neuronal damage of midbrain DA neurons, ultimately improving the symptoms in patients with Parkinson’s disease." (PMID 36009120, 2022). "It was also reported that inhibition of NLRP3 inflammasome could improve brain tissue damage and maintain blood–brain barrier integrity in Parkinson’s and ischemia–reperfusion brain injury." (PMID 36437451, 2022). "SARS-CoV-2 infection manifests in neurological symptoms as well, which also seems to precipitate Parkinson ́s disease according to a preprint publication that suggests that the SARS-CoV-2 spike protein activates the NLRP3 inflammasome ex vivo via ACE-2 interaction in human microglia." (PMID 35626754, 2022). "Furthermore, MPTP-driven NLRP3 inflammasome activation in microglia has recently been shown to play a central role in dopaminergic neurodegeneration and Parkinson’s disease." (PMID 34775541, 2022).
Parkinson disease (continued). "Microglial-mediated neuroinflammation has been reported in many neurodegenerative disorders, and uncontrolled NLRP3 inflammasome activation in microglial cells has been observed in the tissue of the substantia nigra in the midbrain of patients with Parkinson’s disease." (PMID 34775541, 2022). "In addition, inhibiting NLRP3 alleviated α-syn phosphorylation and accumulation in the Parkinson’s disease mice model." (PMID 35431795, 2022). "For instance, the interference of BACE1-AS-regulated ceRNA networks could alleviate neuronal damage; LncGAS5 promotes the progression of Parkinson’s disease (PD) via regulating the miR-223-3p/NLRP3 axis." (PMID 35722589, 2022). "Direct NLRP3 inhibitors as potential Parkinson’s disease (PD) therapeutics at pre-clinical stages." (PMID 36313019, 2022). "Exogenous administration of several miRNAs (miR-30e, miR-190, miR-7) to Parkinson’s disease mice models inhibits NLRP3, ASC, and caspase-1 expression, impairing the release of IL-1β and IL-18, limiting pyroptosis and, consequently, neuroinflammation and neuronal damage." (PMID 34829842, 2021). "Indeed, the role of the best-known NLRP3 inflammasome in the pathogenesis of both Alzheimer’s and Parkinson’s disease is under intensive research." (PMID 34959622, 2021). "Therefore, interaction between miR-7 and SNHG1 leads to elevate NLRP3 expression, resulting in NLRP3 inflammasome activation in Parkinson’s patients." (PMID 34439798, 2021). "Taken together all the reported data suggest a tight connection between mitophagy dysfunction, ROS overproduction, and NLRP3 activation, observed in patients affected by Parkinsonism, confirming the fundamental role of mitochondrial driven neuroinflammation in the development of PD." (PMID 33066071, 2020). "Previous works reveal that the NLRP3 inflammasome contributes to the pathogenesis of a number of neurodegenerative diseases including Alzheimer’s, Parkinson’s disease and Multiple Sclerosis (MS)." (PMID 32517686, 2020). "Similarly, Cao’s study found that long noncoding RNA small nucleolar RNA host gene 1 promoted neuroinflammation in the pathogenesis of Parkinson’s disease via modulating miR-7/NLRP3 pathway." (PMID 31959187, 2020). "Aggregated α-synuclein in Parkinson’s disease could trigger IL-1β generation depending on the NLRP3 inflammasome in brain microglia." (PMID 28928639, 2017). "Similarly, Lee highlighted the role of NLRP3 as a central driver of chronic neuroinflammation in both AD and Parkinson’s disease and suggested that natural product-derived NLRP3 inhibitors may offer therapeutic benefits." (PMID 41601638, 2026). "Conversely, activation of the NLRP3 inflammasome contributes to sustained neuroinflammation, which may be associated with non-motor symptoms such as mood disturbances in Parkinson’s disease." (PMID 41601525, 2026). "However, another study explored the protective effects of quercetin against rotenone-induced Parkinson’s disease via the inhibition of NLRP3 inflammasome activation in microglia and the alleviation of mitochondrial dysregulation in male C57BL/6 J mice (2 months old)." (PMID 41351658, 2025). "Furthermore, the NLRP3 inflammasome plays a critical role in the development of neurodegeneration in Parkinson’s disease, as multiple findings relate the activation of the NLRP3 inflammasome to the advancement of dopaminergic neurodegeneration and the onset of motor symptoms." (PMID 39910608, 2025). "Future studies should focus on identifying the specific binding sites and structure of DJ-1 with NLRP3, as well as investigating whether inhibiting DJ-1 in microglia could serve as a potential therapeutic target for suppressing neuroinflammation in Parkinson’s disease." (PMID 40990010, 2025). "Therefore, strategies aimed at facilitating the parkin-mediated degradation of NLRP3 could provide a therapeutic approach for Parkinson’s disease." (PMID 40307577, 2025).